CD4 (CD4 molecule)
Diseases named in the same sentence as CD4 in open-access papers (continued):
Sharing a sentence is not in itself a finding about the gene and the disease.
Opportunistic infection (continued). "This opportunistic infection has a propensity to invade the central nervous system in immunocompromised individuals, especially in HIV infected patients with CD4 counts < 100 cells/uL." (PMID 28928997, 2017). "Compared with other opportunistic infections, DH presents in patients with HIV that have relatively lower CD4 counts." (PMID 29276711, 2017). "Nevertheless, since T cells can persist and engraft for several months, this raises potential concern regarding prolonged CD4+ cell aplasia by CAR therapy, which can result in deleterious effects not limited to opportunistic infections and viral reactivations." (PMID 29348865, 2017). "In the last 20 years routine T CD4+ lymphocyte (CD4+) cell count has proved to be a key factor to determine the stage of HIV infection and start or discontinue of prophylaxis for opportunistic infections." (PMID 28166729, 2017). "In Ethiopia, CD4+ T-cell counting is still required for all patients at baseline before antiretroviral therapy (ART) and to determine eligibility and follow-up of opportunistic infection prophylaxis." (PMID 28448581, 2017). "In resource-limited countries, CD4 T-cell (CD4) testing continues to be used for determining antiretroviral therapy (ART) initiation eligibility and opportunistic infection monitoring." (PMID 27780216, 2016). "TB is one of the most common opportunistic infections for people infected with HIV, even when CD4 cells count and antiretroviral therapy are taken into account." (PMID 28133458, 2016). "Immunosuppression with a decrease in the CD4+/CD8+ ratio can occur, which leads to development of opportunistic infections, myelosuppression, and gastrointestinal toxicities, including nausea, vomiting, and hepatic lesions." (PMID 26692089, 2016). "Occurrence of opportunistic infections depends on the degree of immunosuppression; PJP and atypical mycobacterioses mainly occur when CD4 cell counts are <200 cells/ml; CMV and disseminated fungal infections are mainly seen when CD4 counts fall <100 cells/ml." (PMID 25972115, 2016). "The main reasons for early mortality have been found to be baseline CD4 cell counts less than 50 cells/μL, advanced WHO stage, and opportunistic infections." (PMID 27820957, 2016). "Enumeration of CD4+ T lymphocytes is important for pre-ART disease staging and screening for opportunistic infections, however access to CD4 testing in resource limited settings is poor." (PMID 27388763, 2016). "However, CD4 testing may remain a valuable tool for managing opportunistic infections." (PMID 27780216, 2016). "However, patients’ CD4 T cell counts, the strongest predictor of subsequent disease progression are close (439, 473 and 491 CD4 T cells/mm3 blood, respectively), and lie above the threshold for the occurrence of most opportunistic infections (200 cells/mm3 blood)." (PMID 27875993, 2016). "It will be critical to expand and decentralize CD4+ T cell testing in order to increase access to ART and ensure appropriate opportunistic infection management of patients on ART." (PMID 26720601, 2015). "In HIV+ patients who exhibit increased CD4+ T cell counts during ART, it has been shown that the ability of PBMC to produce IL-23 is reduced, which compromises the immune response to opportunistic infections." (PMID 26426044, 2015). "In the absence of treatment, most HIV-1 infected individuals will experience a steady decline in the number of CD4+ T-cells, progress to AIDS and eventually die as the result of acquiring opportunistic infections." (PMID 24651404, 2014). "However, it should be noted that malnutrition becomes more likely to occur together with a low CD4 count because of the increased metabolic requirements of uncontrolled HIV, anorexia, malabsorption and opportunistic infections, rather than necessarily being the cause of the low CD4 count." (PMID 25475887, 2014).
Opportunistic infection (continued). "For all HIV-infected adults, including pregnant women, with CD4 cell counts below a given threshold, WHO recommends the use of CTX to prevent opportunistic infections." (PMID 24830749, 2014). "For HIV, these include more rapid HIV testing for early initiation of ART, appropriate monitoring of CD4 T-cell counts, HIV virus load testing, appropriate opportunistic infection prophylaxis, and improvement in ART adherence." (PMID 23622055, 2013). "Candidiasis is the most common opportunistic infection seen in HIV-infected children, particularly in HIV-infected children with persistently low CD4+ counts." (PMID 23510319, 2013). "Sixteen women (7 on placebo, 9 on valacyclovir) had a progression event (death, CD4<250 cells/μl, WHO stage 3–4; or opportunistic infection)." (PMID 22701683, 2012). "For example, some patients had high VLs and low CD4 counts before ART, while others were complicated with opportunistic infections or at different stages of disease progression." (PMID 22701538, 2012). "Important interaction terms such as age*CD4 count (P=0.98), viral Load*CD4 count (P~0.99 for all levels of interaction), viral load*age (P=0.93) and ART status* opportunistic infection status (P~0.90 for all levels of interaction) were also included." (PMID 21537095, 2011). "We aim to assess the effect of selenium supplementation on CD4 cell count, HIV viral load, opportunistic infections, and quality of life in HIV-infected patients in Rwanda." (PMID 21838913, 2011). "The estimation of CD4+ T cell counts is used to decide the initiation of anti retroviral therapy (ART), to monitor the efficacy of ART and to start treatment for opportunistic infections (OIs)." (PMID 21245613, 2010). "While most opportunistic infections commonly occur when CD4 T cell numbers have significantly declined, TB occurs throughout the entire spectrum of HIV disease, including when CD4 T cells numbers are well preserved and stable." (PMID 20224771, 2010). "In contrast to most opportunistic infections, which present in the later stages of HIV infection, TB afflicts HIV-positive individuals throughout the course of infection, even while CD4 numbers are well preserved." (PMID 20224771, 2010). "The amount of CD4 T cells is used for monitoring HIV progression and improvement, and to make decisions to start antiretroviral therapy and prophylactic drugs for opportunistic infections." (PMID 19144106, 2009). "Median survival was significantly lower among children with non-vertical transmission, WHO clinical stage III/IV, CD4 counts below the age-specific threshold, underweight status, and opportunistic infections." (PMID 42116059, 2026). "Being female and having opportunistic infections or AIDS-defining cancers, a CD4 count of less than 200 cells/mm3, and poor social support were identified as significant predictors of depression among people living with HIV attending the ART clinic in the camp." (PMID 40485941, 2025). "He started on ART in 2000 (nadir CD4 300 cells/μL) and remained virally suppressed until the time of death with no history of opportunistic infections." (PMID 40710199, 2025). "Negative correlation of hsCRP with CD4 cell counts was possibly due to increase immune activation and viral loads-mediated increase destruction of CD4-T cells and concurrent opportunistic infections that increase hsCRP levels." (PMID 39834358, 2025). "However, it continues to be a major opportunistic infection among individuals with HIV and low CD4 T cell counts, particularly those who are unaware of their infection or are untreated/abandoned." (PMID 41375872, 2025). "Female sex (AOR = 2.6; 95% CI: 1.24, 6.28), opportunistic infections (AOR = 3.00; 95% CI: 1.75, 7.06), a CD4 count < 200 cells/mm3 (AOR = 2.40; 95% CI: 1.78, 8.23), and poor social support (AOR = 4.70; 95% CI: 1.98, 9.79) were significantly associated with depression among the refugees." (PMID 40485941, 2025).
Opportunistic infection (continued). "The study included 14 PWH with CD4 counts > 200 for at least 6 months, no prior opportunistic infections, and undetectable HIV viral loads for at least 3 months for kidney transplant and predicted ability to achieve HIV suppression for liver transplant." (PMID 40113607, 2025). "However, opportunistic infections, in general, are unlikely in patients maintained on a stable ART regimen, even with CD4 counts <200 cells/μL, especially if the patient is taking a prophylactic regimen against toxoplasmosis." (PMID 41246707, 2025). "This pattern highlights the continued vulnerability of ART-naïve or non-adherent individuals to opportunistic infections, even at moderately preserved CD4 counts." (PMID 40700328, 2025). "When the CD4 + T-cell count is less than 200 and the CD4+/CD8 + T-cell ratio is less than 0.20, the likelihood of developing multiple opportunistic infections increases, as does the likelihood of multiple infections occurring simultaneously with the progression of the disease." (PMID 38720250, 2024). "Individuals testing RTRI-recent with CD4 counts >200 cells/mm3, no opportunistic infections, and not on antiretroviral treatment were classified as RITA-CS-recent." (PMID 39724047, 2024). "The current diagnostic criteria for IRIS require the following: Presence of an atypical opportunistic infection, a decrease in the level of HIV RNA by at least 1 log10 copies/ml, an increased blood CD4+ T-cell count after HAART, and an increase in immune response to a specific pathogen." (PMID 39119403, 2024). "Several factors were associated with an increased risk of death, including older age, poor functional status, extra-pulmonary TB, advanced WHO stage, opportunistic infections, low CD4 count, and lack of co-trimoxazole prophylaxis." (PMID 39095740, 2024). "Nearly 70% of HTXs were classified as "late presenters" (LPs), indicating individuals diagnosed with either a CD4+ T cell count below 350 cells/μL or diagnosed with an opportunistic infection, regardless of the CD4+ T cell count at the time of diagnosis." (PMID 39339921, 2024). "The main characteristics of this population analysed are: men 29/34 (85.29%), mean age 55.6 years, mean time of HIV infection 18.5 years, mean CD4 nadir 327.44, previous diagnosis of advanced HIV in 10/34 (29.41%) and previous opportunistic infection in 7/34 (20.6%)." (PMID 39513741, 2024). "The high burden of AHD in both groups also supports the fact that CD4 + count and screening for opportunistic infections such as TB are recommended in PLHIV regardless of the setting in which they received care." (PMID 38902606, 2024). "Assessing the immune status of patients through point-of-care (POC) CD4+ T lymphocyte counts is essential for identifying individuals with advanced HIV disease, who should be prioritized for prophylaxis against opportunistic infections, even if they are asymptomatic." (PMID 39768973, 2024). "Even patients with baseline CD4 + T cell counts < 200 cells/mL, VL ≥ 400, or opportunistic infections tolerate ICI well and do not show increased irAE compared to the uninfected population." (PMID 39609320, 2024). "CD4 T-lymphocyte count is monitored four to six months after the initiation of ARV to assess the immunological response to ART and to assess the need to discontinue opportunistic infection prophylaxis." (PMID 39435225, 2024). "Included in their cost analyses were ART, laboratory testing for HIV monitoring (CD4 and viral load), and treatment for opportunistic infections, which we did not." (PMID 39014381, 2024). "He had an undetectable HIV load (< 50 copies/ ml) and a stable CD4 T-cell count (> 200 cells/ ul), with no opportunistic infection 43 months after LT." (PMID 38589801, 2024). "The identified problems included a lack of viral load testing (41, 100%), lack of CD4 count monitoring (15; 36.6%) and lack of prophylactic treatment against opportunistic infections (10; 24.4%)." (PMID 38633911, 2023).
Opportunistic infection (continued). "Sex, age, marital status, nationality, occupation, and CD4 + T-cell counts were significantly different between patients without opportunistic infections and those with opportunistic infections (P < 0.05)." (PMID 36413338, 2023). "Children with opportunistic infections had major negative impacts on CD4 cell count changes over time." (PMID 38087261, 2023). "No significant spirometric differences were observed among CD4 or viral load groups (p>0.05), nor with opportunistic infections (p>0.05)." (PMID 38022158, 2023). "For patients with a single opportunistic infection, loading coefficients (length of the projection of variables on the PC1 axis), in general, showed variables closely related to PC1, with LYMPH, CD4, and CD3 having a strong influence on PC1 (quality correlation >0.6)." (PMID 37816066, 2023). "However, in this study, patients with active opportunistic infections or other AIDS-defining diseases were excluded, and only 10% of the patients had baseline CD4 < 200 cells/μL." (PMID 37243208, 2023). "of infections in 252 patients with CVID, 16 (6%) patients presented with opportunistic infections like CMV or Pneumocystis jirovecci pneumonia (PCP) but we do not know the CD4 levels of the afflicted patients." (PMID 37180118, 2023). "Individuals with chronic HIV infection not on treatment with antiretroviral agents, as the CD4 + T-cell counts drop, are vulnerable to a multitude of infections that rarely occur in an immunocompetent host, hence the term opportunistic infections (OIs)." (PMID 36413338, 2023). "The incidence of opportunistic infections per 100 PYO was found to be higher in children with anemia (24.75), those with a CD4 cell count below the threshold (18.71), those who reported never taking CPT (16.82) or TPT (15.76), and those who ever exhibited fair or poor adherence to ART (18.94)." (PMID 37205221, 2023). "Markers of advanced disease (opportunistic infection, high viral load, low CD4), side effects, comorbidities and lack of ART adherence negatively impacted HRQoL for PWH experiencing virological failure." (PMID 37605150, 2023). "Other study indicated that, weight, CD4 cells < 350/mm3, tuberculosis co-infection, advanced WHO stage, other opportunistic infections, having poor adherence to ART, rural residence, and eating non-diversified foods were significantly associated with low hemoglobin level." (PMID 38042846, 2023). "His CD4 count was > 400 cells/mm3, viral load was largely suppressed with a few interruptions in therapy due to side effects, and he had no history of opportunistic infections." (PMID 37568163, 2023). "Even patients who do not have optimal improvement in their CD4 count have a low incidence of opportunistic infection if they are able to keep their viral load suppressed for long periods." (PMID 35456055, 2022). "The ratio of CD4 + and CD8 + T cells, which is closely related to opportunistic infections, was 0.3, indicating cellular immune dysfunction and a higher probability of opportunistic infection." (PMID 36550574, 2022). "For patients with low dose EFV (400mg), whose median BMI (P = 0.016), rates of high VL (VL ≥ 100,000 copies/mL, P=0.014) and opportunistic infections (P < 0.001) were lower than with DTG, while median CD4+ T-cell count (P = 0.002) and CD4/CD8 ratio (P < 0.001) were higher." (PMID 36700216, 2022). "We evaluated biomarkers such as age, gender, CD4 cell count and CD4:CD8 ratio at the beginning of the therapy, HIV viral load at the beginning of ART, the existence of acute HIV infection, HCV or HBV coinfections, comorbidities or opportunistic infections." (PMID 36298842, 2022). "Low hemoglobin levels (10 mg/dl), low CD4 counts or percentages, clinical stages III and IV, and non-users of CPT were all associated with higher rates of opportunistic infection." (PMID 36536709, 2022).
Opportunistic infection (continued). "Although CD4 counts no longer influence the decision to start ART, they are crucial to inform opportunistic infection risk stratification, targeted clinical management, and advanced disease care packages." (PMID 34309633, 2022). "CD4 T-cell counts obtained in 5 patients at 18-24 months after treatment ranged from 0.19 to 0.40 × 109/L, although we recorded no opportunistic infections." (PMID 35641232, 2022). "Multivariate logistic regression analysis indicated that none of age, opportunistic infections, CD4 cell counts, and HIV-1 viral loads > 100,000 copies/mL were independently associated with treatment outcome." (PMID 34983415, 2022). "Outcomes included proportion of participants virally suppressed and with no new opportunistic infections, and mean CD4 cell count." (PMID 34427813, 2022). "Since we did not have CD4 + counts, we included opportunistic infections which occur more frequently in people with advanced HIV." (PMID 34326369, 2021). "In the study published by Hadadi on HIV patients with a CD4 count >200 cells/mm3, a zinc deficiency of 44% was found, and after its supplementation, a reduction in opportunistic infections or an increase in the CD4 count was not demonstrated." (PMID 33481813, 2021). "But, variables like presence of opportunistic infections at the moment of diagnosis and CD4 cells/count were not included in the Cox model because the p-value at bi-variable analysis was greater than 0.2." (PMID 33989330, 2021). "The clinical presentation of HIV-KS is variable; frequently it is presented as cutaneous lesions with a CD4 cells count ≥200 cells/mL and no opportunistic infection ongoing, and it is defined as stage T0." (PMID 34831094, 2021). "The immunodeficiency-associated variant is seen primarily in individuals with HIV infection counterintuitively with higher CD4 counts, and generally in the absence of opportunistic infections." (PMID 32782017, 2020). "CD4+ count ≥ 200 cells/μL (≥ 100 cells/μL can be considered for liver transplant recipients provided there is no history of opportunistic infections or malignancies)." (PMID 33240537, 2020). "One study mandated a CD4 cell count of greater than 200 cells/μL off all ART without evidence of opportunistic infection for 60 days prior to randomization." (PMID 33258905, 2020). "Research suggest that patients with low CD4 cell counts are likely to be in WHO stage 3 or 4, have opportunistic infections, and are too sick to present for follow-up or might have even died unbeknown to the health providers." (PMID 33505567, 2020). "Effective ART improves the immune system, and most of the CD4 count of those with regular ART was at a relatively normal count (over 200/μL), which might reduce the chance of opportunistic infection." (PMID 32818208, 2020). "Perceived stigma, younger age, widowed, being symptomatic, fair and poor adherence, recent opportunistic infection, low CD4 count, and HIV status not disclosed were positively associated with depression." (PMID 32742304, 2020). "Opportunistic infections had major negative effects on CD4 count changes over time, suggesting that children with opportunistic infections had lower CD4 counts." (PMID 32476985, 2020). "Studies have also shown a relationship between CD4 counts and the nutritional status of the children reporting that malnutrition weakens the immune response to ART there by creating a time gap where the child is still prone for opportunistic infections (OIs)." (PMID 31781388, 2019). "Patients with opportunistic infections such as human papillomavirus (HPV), HIV, aspergillus, Pneumocystis carinii (PC), and Cryptococcus neoformans (CN) infection showed significantly lower number of CD4+ T cells and NK cells than healthy controls." (PMID 31857499, 2019). "CD4 testing remains necessary for identifying individuals with advanced HIV disease (i.e. low CD4 count) and guiding CrAg screening and other preventive measures against common opportunistic infections." (PMID 31803848, 2019).